KLHL9 (kelch like family member 9)
Description:
Substrate-specific adapter of a BCR (BTB-CUL3-RBX1) E3 ubiquitin-protein ligase complex required for mitotic progression and cytokinesis. The BCR(KLHL9-KLHL13) E3 ubiquitin ligase complex mediates the ubiquitination of AURKB and controls the dynamic behavior of AURKB on mitotic chromosomes and thereby coordinates faithful mitotic progression and completion of cytokinesis.
Synonyms: KIAA1354; FLJ13568
Tractability: Small molecule: it belongs to a druggable protein family. PROTAC: ubiquitination databases record sites on it; its protein half-life has been measured.
Gene: Protein-coding gene on chromosome 9 (21,320,024 to 21,335,404, reverse strand). Ensembl gene ENSG00000198642.
Subcellular location (Human Protein Atlas): Cytosol
Pathways (Reactome):
Immune System: Antigen processing: Ubiquitination & Proteasome degradation
Metabolism of proteins: Neddylation
Gene Ontology:
Molecular function: cullin family protein binding; protein binding; ubiquitin-protein transferase activity; ubiquitin-like ligase-substrate adaptor activity
Biological process: protein ubiquitination; regulation of cytokinesis; proteasome-mediated ubiquitin-dependent protein catabolic process
Cellular component: Cul3-RING ubiquitin ligase complex; midbody; cytosol
Genetic constraint (gnomAD): Loss-of-function variants: 27 observed, 44.61 expected, observed/expected ratio (o/e) 0.61, 90% interval 0.44 to 0.83. The upper end of that interval is the gene's LOEUF score, 0.83, which puts it in group 3 of 6, group 1 being the genes least tolerant of losing a copy. Missense variants: 629 observed, 793.89 expected, observed/expected ratio (o/e) 0.79, 90% interval 0.74 to 0.85. Synonymous variants: 274 observed, 270.41 expected, observed/expected ratio (o/e) 1.01, 90% interval 0.92 to 1.12.
Homologues: Orthologues: macaque KLHL9 (100% identical), pig KLHL9 (99% identical), rabbit KLHL9 (99% identical), rat Klhl9 (99% identical), mouse Klhl9 (99% identical), chimpanzee KLHL9 (98% identical), tropical clawed frog klhl13 (93% identical), zebrafish klhl13 (90% identical). Paralogues in human: KLHL13 (92% identical), KLHL26 (41% identical), KLHL36 (34% identical), KLHL31 (33% identical), KLHL14 (32% identical), KLHL32 (31% identical), KLHL22 (31% identical), KLHL34 (30% identical), KLHL5 (29% identical), KLHL15 (28% identical), KLHL4 (28% identical), KLHL28 (27% identical), and 42 more.
Diseases named in the same sentence as KLHL9 in open-access papers:
KLHL9 is named in the same sentence as 16 diseases in open-access papers, as found by Europe PMC text mining. Sharing a sentence is not in itself a finding about the gene and the disease. The quoted sentences say what the papers report.
distal myopathy (3 papers, 2014 to 2024). Distal myopathy refers to a group of muscle diseases which share the clinical pattern of predominant weakness and atrophy beginning in the feet and/or hands. "For instance, KLHL9- and ADSSL1-associated distal myopathies are reported to have a rather early onset between 10 and 20 years of age, while first symptoms in MYOT-associated distal myopathy are occurring between 50 and 60 years of age." (PMID 32361838, 2020). "The first Kelch protein defect reported in a primary skeletal muscle disease was of KLHL9, resulting in an early onset autosomal dominant form of distal myopathy." (PMID 24959344, 2014). "Moreover, in distal myopathy, the interaction of mutant KLHL9 with Cul3 is highly reduced in comparison to wild-type KLHL9, which may in turn affect the ubiquitination of cellular proteins." (PMID 24959344, 2014). "In contrast, relevant similarities were observed in 6 distal myopathies (TIA1, late-stage TTN, MYOT, SQSTM1/TIA1, KLHL9, ADSSL1)." (PMID 32361838, 2020).
Insulin resistance (3 papers, 2021 to 2024). Increased resistance towards insulin, that is, diminished effectiveness of insulin in reducing blood glucose levels. "Analogously, the insulin receptor substrate-1 has been implicated in regulating insulin resistance via proteasomal degradation mediated by KLHL9/KLHL13/CUL339." (PMID 38834545, 2024). "While the KLHL9/KLHL13/CUL3 complex has been primarily implicated in regulating cell cycles, insulin resistance and cancer, its role in infectious diseases has remained largely unexplored." (PMID 38834545, 2024). "In addition, Kelch-like family member 9 (KLHL9) can induce insulin resistance by regulating insulin receptor substrate-1 (IRS1) degradation." (PMID 34516309, 2021).
and nemaline myopathy (1 paper, 2020). "KLHL9, KBTBD13, KLHL40, and KLHL41 have been implicated in distal and nemaline myopathy." (PMID 31985165, 2020).
autosomal dominant distal myopathy (1 paper, 2024). Autosomal dominant form of distal myopathy. "The mutation of the BTB domain in KLHL9 (Kelch-like family member 9), which disrupts KLHL9 binding to CLR3, was found to be associated with a unique form of early-onset autosomal-dominant distal myopathy in human patients." (PMID 38334627, 2024).
glioma (1 paper, 2019). A benign or malignant brain and spinal cord tumor that arises from glial cells (astrocytes, oligodendrocytes, ependymal cells). "By performing a systematic analysis of the CNV-driven ceRNAs with clinical features, we found that the CNVs of some genes (such as MTAP/CDKN2A/CDKN2B/KLHL9) had significant impacts on histological diagnosis and survival in glioma." (PMID 31719831, 2019). "Interestingly, CDKN2B, CDKN2A, MTAP, and KLHL9 also belonged to the largest community in the dysregulated ceRNA network, suggesting their possible role to inhibit the development of glioma together." (PMID 31719831, 2019).
melanoma (1 paper, 2008). A malignant, usually aggressive tumor composed of atypical, neoplastic melanocytes. "Beside its genomic location at 9p21, KLHL9 appeared to represent a good candidate for melanoma susceptibility as it has been reported that loss of function of BTB/kelch repeat proteins may contribute to tumorigenesis." (PMID 18612309, 2008). "The finding of the 5′UTR variant within KLHL9, located 630 kb from CDKN2A on 9p21 in one melanoma patient was serendipitous." (PMID 18612309, 2008). "Although the 5′UTR variant within KLHL9 was absent in a French control population, we ruled out major involvement of KLHL9 in the susceptibility to melanoma by screening the entire coding sequence of the candidate gene in a panel of 42 high-risk CMM families." (PMID 18612309, 2008).
cancer (3 papers, 2016 to 2022). A tumor composed of atypical neoplastic, often pleomorphic cells that invade other tissues. "KLHL9 has not been implicated in cancer, but highly homologous members of the KLHL family have such as KEAP1 and KLHL20 – both of which are notable tumour suppressors." (PMID 26781748, 2016). "The genes that had a high expression when compared to the control group, low standard deviation and repeat in multiple cancer types are TMEM125,C1orf172 and KLHL9." (PMID 31831960, 2019). "KLHL9, LCMT2, and LZTR1 have been reported to influence cancer progression in different contexts." (PMID 35656299, 2022).
tumor (3 papers, 2012 to 2018). "Indeed, by correlating gene expression with zygosity status, they found that CDKN2A expression levels were normal or even elevated when associated at heterozygous gene loss, and proposed rather that KLHL9 and MTAP would concurrently and in a context-dependent manner promote tumor aggressiveness." (PMID 30558563, 2018).
infection (1 paper, 2024). The state of being infected such as from the introduction of a foreign agent such as serum, vaccine, antigenic substance or organism. "Nevertheless, the mRNA level of Immt showed no significant changes no matter when Cul3, Klhl9 or Klhl13 was knocked down after B. pseudomallei WT or ΔbipD infection." (PMID 38834545, 2024).
infectious disease (1 paper, 2024). A disorder directly resulting from the presence and activity of a microbial, viral, or parasitic agent in humans. "Although evidently not involved in regulation of infectious diseases, KLHL9/KLHL13/CUL3 E3 ligase complex was essential for BipD-dependent ubiquitination of mitochondria in mouse macrophages." (PMID 38834545, 2024).
KLHL9 also shares sentences with these, for which no sentence is quoted: Anosmia (1 paper); cardiomyopathy (1); congenital nemaline myopathies (1); COVID-19 (1); epidermolysis bullosa simplex (1); myopathy (1).